TNFRSF18 (TNF receptor superfamily member 18)
Diseases named in the same sentence as TNFRSF18 in open-access papers (continued):
Sharing a sentence is not in itself a finding about the gene and the disease.
cancer (continued). "Strong and consistent positive correlations were witnessed between ADM and several immune checkpoint genes, including CD274 (PD-L1), CD276, TNFRSF18, TNFSF9, and PVR in pan-cancer analysis, indicating its role in the development of suppressive immune microenvironment and T cell exhaustion." (PMID 40529377, 2025). "However, it was noteworthy that among these immune-related genes, CD274, CD276, TNFRSF18, TNFSF9, and PVR displayed strong correlations with ADM expression across almost all cancer types." (PMID 40529377, 2025). "T-cell co-stimulatory receptors that belong to the tumor necrosis factor receptor superfamily (TNFRSF), including OX40 receptor (CD134; TNFRSF4), 4-1BB (CD137; TNFRSF9), and glucocorticoid-induced TNFR-related (GITR) protein (CD357; TNFRSF18), are potential targets for cancer immunotherapy." (PMID 38526805, 2024). "Correlation analysis between RFC4 and checkpoint gene expression in different types of cancers showed a high correlation with immune genes including CCL4, CCL16, HLA family genes, TNFRSF8, TNFRSF14, TNFRSF18, CD70, CD44 (p < 0.05), CD276, CX3CL1 and VGEGFA (p < 0.05)." (PMID 39031628, 2024). "In diverse cancer types, correlation analysis between CDCA4 and checkpoint gene expression indicated a high connection (P<0.05) with TNF-related immune genes including TNFRSF8, TNFRSF14, TNFRSF18, CD70, CD44, and CD276 (B7-H3)." (PMID 35251007, 2022). "In addition, five PRIs (HHLA2, IL2RA, TNFRSF18, TNFSF14, and CTLA4) included in the signature were regarded as potential PLAUR-related biomarkers in KIRC, which were studied in other cancers including KIRC based on the current literature." (PMID 36052236, 2022). "In diverse cancer types, the correlation between OAS3 and the expression of checkpoint genes indicated a high correlation with TNF-related immune genes including TNFRSF14, TNFRSF8, TNFRSF25, TNFRSF4, TNFRSF18, TNFSF15, and TNFRSF9." (PMID 35592250, 2022). "The co-stimulatory glucocorticoid-induced TNFR related protein (GITR, also known as TNFRSF18) is a potent target for immunotherapy in mouse models of cancer and chronic infection, owing to its capacity to concurrently promote effector T-cell function and dampen Treg-mediated suppression." (PMID 35123267, 2022). "Similar to PD-L2, no knockout study of TNFRSF18 (GITR) to dissect its role in cancer was found currently." (PMID 31358815, 2019). "Among the remaining 8 DEGs (ADRA2A, P2RX6, XCL2, XCL1, CCL7, TRIM54, TNFRSF18 and SPOCK1), the expression of ADRA2A, the top one, in KIRC based on individual cancer is lower than the normal tissues, but patients with lower expressed ADRA2A have a better overall survival (OS)." (PMID 31159832, 2019). "Notably, TNFRSF18, LAG3, and PVR exhibit significant differences in 13 to 15 cancers." (PMID 40867324, 2025). "However many other conventional immune checkpoints such as TIGIT, TNFRSF4 (OX40 receptor/CD134), TNFRSF9 (4-1BB/CD137), and TNFRSF18 (GITR) are not universally overexpressed in cytotoxic CD4+ T cells from cancer patients." (PMID 34910940, 2021).
TNFRSF18 also shares sentences with these, for which no sentence is quoted: infection (34 papers); Autoimmunity (15); ovarian carcinoma (11); asthma (10); viral infections (10); influenza infection (9); colitis (8); Sjögren’s syndrome (7); atherosclerosis (6); systemic lupus erythematosus (6); type 1 diabetes (6); bladder cancer (5); parasitemia (5); COVID-19 (4); gastric cancer (4); Insulin resistance (4); rheumatoid arthritis (4); Allergy (3); brain tumors (3); eosinophilia (3); gastritis (3); graft versus host disease (3); Hashimoto thyroiditis (3); inflammation (3); inflammatory bowel disease (3); mesothelioma (3); myocarditis (3); non-small cell lung carcinoma (3); osteosarcoma (3); periodontitis (3).
A further 101 diseases each share a sentence with TNFRSF18 in 3 papers or fewer.